RN7SKP63 (RN7SK pseudogene 63)
Gene: Miscellaneous RNA gene on chromosome 22 (21,389,191 to 21,389,491, forward strand). Ensembl gene ENSG00000200057.
Homologues: Orthologues: chimpanzee 7SK (99% identical), guinea pig 7SK (63% identical). Paralogues in human: RN7SKP131 (100% identical), RN7SKP221 (99% identical), 7SK (79% identical), RN7SKP71 (79% identical), RN7SKP78 (78% identical), RN7SKP176 (77% identical), RN7SKP203 (77% identical), RN7SKP189 (76% identical), RN7SKP9 (76% identical), RN7SKP50 (76% identical), RN7SKP20 (75% identical), RN7SKP79 (75% identical), and 284 more.